RN7SL769P (RNA, 7SL, cytoplasmic 769, pseudogene)
Gene: Miscellaneous RNA gene on chromosome 12 (110,360,452 to 110,360,746, reverse strand). Ensembl gene ENSG00000276956.
Homologues: Orthologues: chimpanzee Metazoa_SRP (99% identical), macaque Metazoa_SRP (94% identical), guinea pig Metazoa_SRP (64% identical). Paralogues in human: RN7SL2 (90% identical), RN7SL1 (89% identical), RN7SL3 (87% identical), RN7SL45P (86% identical), RN7SL444P (86% identical), RN7SL220P (85% identical), RN7SL451P (84% identical), RN7SL127P (84% identical), RN7SL712P (84% identical), RN7SL743P (83% identical), RN7SL300P (83% identical), RN7SL336P (83% identical), and 706 more.